CD34 (CD34 molecule)
Diseases named in the same sentence as CD34 in open-access papers (continued):
Sharing a sentence is not in itself a finding about the gene and the disease.
cervical carcinoma (10 papers, 2014 to 2023). A carcinoma arising from either the exocervical squamous epithelium or the endocervical glandular epithelium. "Our study has uncovered that positive CD34 expression before NACT are significantly associated with effective NACT in cervical cancer." (PMID 33392721, 2021). "An immunohistochemical study was shown that high CD34 expression was significantly associated with tumor size, tumor stage and lymph node metastasis in cervical cancer." (PMID 33392721, 2021). "Other investigators have also noted significant peritumoral tissue changes characterized by the loss of CD34 and a gain of α-SMA expression in the stroma surrounding cervical cancers and pre-cancerous lesions." (PMID 37919378, 2023). "CD34 counts in cervical cancer (20.35 ± 5.82) were significantly higher than in normal cervix tissue (5.98 ± 2.77) (P<0.05)." (PMID 36324571, 2022). "As a transmembrane glycoprotein expressed in capillary endothelial cells, CD34 is a useful angiogenesis marker reflecting the grade of microvascular modeling in cervical cancer." (PMID 36324571, 2022). "This study found that the expression of CD34 in cervical cancer tissue was significantly higher than that in normal cervix tissue, indicating that there is an increased neovascularization in cervical cancer tissue." (PMID 36324571, 2022). "CD34 count and Ki-67 PI in cervical cancer were significantly higher than in normal cervix tissue (p<0.05)." (PMID 36324571, 2022). "Immunohistochemical staining of CD34 before NACT helps to develop individualized treatment of cervical cancer patients." (PMID 33392721, 2021). "We, therefore, suggest that CD34 expression is suited to be the predictive biomarker of NACT response in cervical cancer." (PMID 33392721, 2021). "MVD, as assessed by CD34 staining, was significantly increased in cervical cancer compared with normal." (PMID 28584715, 2017). "However, measured Vp values in TKMs were smaller in cervical cancer than in normal cervix tissue, and showed little correlation with the expression of CD34." (PMID 36324571, 2022). "However, up until now, less study has been dedicated to clarify the association between CD34 or Bcl-2 expression and the response to NACT in cervical cancer." (PMID 33392721, 2021). "CD34, a transmembrane glycoprotein expressed in capillary endothelial cells, is a useful angiogenesis marker reflecting the grade of microvascular modeling in cervical cancer." (PMID 33392721, 2021). "The most significant factors from the point of view of early cervical cancer prognosis were DCs with a weak expression of CD34, “contact type DCs,” capillaries in the tumor solid component, and lymphatic vessels in the lymphoid and polymorphic cell infiltrates of tumor stroma." (PMID 32849870, 2020). "However, there was no statistical significance in the association between the levels of MVD assessed by anti-CD31, CD34 or CD105 with the prognosis of cervical cancer patients for OS or DFS." (PMID 30305802, 2018). "The analysis showed that DCs with a weak expression of CD34, “contact type” DCs, capillaries in the tumor solid component, and lymphatic vessels in the lymphoid and polymorphic cell infiltrates of the tumor stroma are the most significant factors in terms of cervical cancer prognosis." (PMID 32849870, 2020). "Using ToppCluster to generate a network of genes shared between Tgfbr2 deficient CD34+ anorectal transitional SCC cells and published datasets of aggressive human cancers we found that a number of genes were commonly overexpressed in human cancers including cervical carcinoma." (PMID 28219480, 2017). "The aim of this study was to evaluate the predictive value of CD34 and Bcl-2 in the NACT effectiveness of cervical cancer." (PMID 33392721, 2021). "The present study revealed a positive relationship between the pre-NACT expression of CD34 and the efficacy of NACT in cervical cancer." (PMID 33392721, 2021).
cervical carcinoma (continued). "Recently, other antibodies were used to assess the counts of MVD in cervical cancer, such as CD31 (also known as platelet endothelial cell adhesion molecule), CD34 and CD105 (also known as Endoglin)." (PMID 30305802, 2018). "Correlations between DCE-MRI parameters and CD34 in cervical cancer or normal cervix tissue were largely weak or not correlated, except for Fp from ATH in normal cervix tissue (r=-0.622, P<0.05)." (PMID 36324571, 2022). "However, further researches are still required to investigate the roles of CD34 and Bcl-2 in NACT for patients with cervical cancer." (PMID 33392721, 2021). "Therefore, we considered that no statistical significance of relationship between counts of MVD assessed by other biomarkers including CD31, CD34 and CD105, and prognosis of cervical cancer patients was limited by a few number of related studies." (PMID 30305802, 2018). "The positive CD34 expression before NACT may serve as a predictive biomarker for NACT of cervical cancer, but the pre-NACT expression of Bcl-2 is not an independent predictor." (PMID 33392721, 2021). "Therefore, to determine the utility of CD34 and Bcl-2 expression as predictive biomarkers, we investigate the relationship between the expression of two biomarkers before NACT and the efficacy of NACT in cervical cancer." (PMID 33392721, 2021). "Thus, the down-regulated expression of CD34 and Bcl-2 may reflect an efficient NACT response in cervical cancer." (PMID 33392721, 2021). "It was turned out that Ktrans of Tofts or Ex-Tofts, Vp of three 2CXMs, Fp of ATH, and DP, showed moderately negative correlation with Ki-67 in cervical cancer tissue, and Fp of ATH showed moderately negative correlation with CD34 in normal cervix tissue." (PMID 36324571, 2022). "When evaluating angiogenesis activity using antibodies to CD31, CD34, or CD105, correlations of MVD with cervical cancer prognosis were not revealed." (PMID 32849870, 2020).
erythroleukemia (10 papers, 2012 to 2025). Acute erythroid leukemia characterised by the presence of at least 50% erythroid precursors and at least 20% myeloblasts in the bone marrow. "Since K562 cells arose from a CML associated erythroleukemia, we examined relative levels of DLGAP1 mRNA in a database at the FHCRC of patient samples in all the phases of CML as well as normal CD34 cells." (PMID 31321035, 2019). "Acturally, K562, as an erythroleukemia cell line, fail to mimic every features of normal human CD34+ cell differentiation into red cells." (PMID 22235304, 2012). "To obtain the bone marrow-like conditions, we opted for the co-culture model, which allows intercellular cross-talk and interactions between human erythroleukemia K562 or primary CD34 + CML cells growing in suspension and HS-5 stromal cells growing as an attached layer." (PMID 41331927, 2025). "Consequently, vector pEPβ-globin was used to transfect cells of haematopoietic origin, namely the established human erythroleukemia K562 cell line and the haematopoietic progenitor CD34+ cells, to investigate the vector’s specific transfection parameters." (PMID 37761914, 2023). "A primitive CD34+ subpopulation of a human erythroleukemia multidrug-resistance cell lineage (K562), possesses greater resistance to imatinib than the majority CD34- population sensitive to the elevated ROS levels by the combination of simvastatin and imatinib." (PMID 24365069, 2013). "In addition, miR-221 has been found to lead to the minimization of stem cell repopulating activity in cord blood CD34+ cells by targeting KIT, while they also act as inhibitors in the proliferation process of erythroleukemia cell lines." (PMID 35163198, 2022).
invasive breast carcinoma (10 papers, 2002 to 2025). A carcinoma that infiltrates the breast parenchyma. "In invasive breast carcinoma, the loss of CD34+ fibroblasts is accompanied by the emergence of α-SMA+ myofibroblasts, also known as cancer-associated fibroblasts (CAFs)." (PMID 39056788, 2024). "The current study demonstrated quantitative differences in telocyte marker expression—specifically vimentin, CD10, CD34, and c-Kit—across molecular subtypes of invasive breast cancer." (PMID 40724542, 2025). "Our study has shown that fibroblast CD34 expression is consistently lost in invasive breast carcinomas, and in a high proportion of cases of DCIS, particularly necrotic and/or high-grade lesions, which are thought to be more likely to progress to invasion." (PMID 23469238, 2013). "Together with the reduction of Lin-/HLA-DR+ DCs, we observed a statistically significant increase of CD34+ cells in the peripheral blood of patients with invasive breast cancer." (PMID 14562018, 2003). "In invasive breast cancer, CD34 has been shown to yield higher microvessel values than CD31 or factor VIII and does not stain any tumour or inflammatory cells as CD31 or factor VIII." (PMID 12232748, 2002). "Paraffin-embedded sections of 177 primary invasive breast cancer, with complete clinical follow-up information for 10 years, were stained for VEGF-A, -C, -D, podoplanin and CD34 using standard immunohistochemical approaches." (PMID 17353919, 2007). "But the majority of tumor stroma in ductal carcinoma in situ(DCIS) and invasive breast cancer of no special type (IBC-NST) were characterized by α-SMA positive myofibroblasts rather than CD34+ fibroblasts, several CD34+ fibroblasts are preserved in invasive lobular carcinomas (ILC)." (PMID 37496657, 2023).
lipoma (10 papers, 2016 to 2025). A benign, usually painless, well-circumscribed lipomatous tumor composed of adipose tissue. "Additionally, sclerotic lipomas are composed of cytologically bland spindle cells that lack CD34 expression, embedded in dense fibrosclerotic stroma, and with randomly dispersed adipocytes as a minor component." (PMID 40376352, 2025). "Adipose stromal cells can participate in the development of lipomas, which contain CD34+ cells." (PMID 33353193, 2020). "CD34-positive ASCs have been reported to undergo proliferation in benign lipomas." (PMID 27376027, 2016). "Spindel cell lipomas consist of bland spindle cells and are positive for CD34 and negative for MDM2 and CDK4." (PMID 40777097, 2024). "Immunohistochemical analysis of these lipomas revealed that the spindle cells were positive for vimentin and CD34, and negative for S-100 protein and muscle-specific actin." (PMID 31041916, 2019). "Hibernoma, however, is distinguished from lesions such as spindle cell/pleomorphic lipoma and haemosiderin fibrohistiocytic lipomatous tumour by the absence of CD34 expression and staining for UCP1 (at high dilution of the antibody)." (PMID 31114671, 2019).
lymph node metastasis (10 papers, 2005 to 2025). "By contrast, an association was found between the number of CD34-positive lymphatic vessels and lymph node metastasis in the deepest tumor infiltration zone (p < 0.05)." (PMID 40243510, 2025). "Stromal loss of CD34+ fibroblasts correlated with the presence of lymph node metastases and, in addition, with worse overall and disease-free survival." (PMID 32435886, 2020). "However, an association was observed between the number of CD34-positive lymphatic vessels and lymph node metastasis." (PMID 40243510, 2025). "We analyzed the correlation between YKL-39, CD68, and CD34 expression and patient gender, age, depth of tumor infiltration, lymph node metastasis, distant metastasis, TNM stage, and degree of differentiation." (PMID 36372883, 2022). "Since we previously found that the decrease in CD34-MVD was associated with tumor invasion events (tumor enlargement and lymph node metastasis), thus explaining the favorable prognosis of patients with high CD34-MVD and the poor prognosis of those with low CD34-MVD." (PMID 39906069, 2025). "CD34-MVD was associated with tumor size, lymph node metastasis, tumor recurrence, and patient survival status; patients with tumor size ≤3 cm (P = 0.015), negative for lymph node metastasis (P = 0.049), no tumor recurrence (P = 0.021), and survival (P = 0.042) had higher MVD." (PMID 39906069, 2025). "The correlation between lymph node metastasis and CD34 count was significant (0.0001, S)." (PMID 38130549, 2023). "It is reported that circulating CD34+VEGFR-3+ lymphatic/vascular endothelial progenitor cells correlate with lymph node metastasis in patients with epithelial ovarian cancer, and further study revealed that CD34+/VEGFR-3+ EPCs in human cord blood could differentiate into lymphatic endothelial cells." (PMID 27698675, 2016). "The proportion of patients with high expression of CD34 was significantly higher in patients with lymph node metastasis than in those without lymph metastasis (69.0% vs. 41.3%, χ2 = 5.452, P = 0.020)." (PMID 32962642, 2020). "Our findings revealed that CD34-MVD was higher in patients with tumor size ≤3 cm than in those with tumor size >3 cm, and higher in patients without lymph node metastasis than in those with lymph node metastasis." (PMID 39906069, 2025).
metabolic syndrome (10 papers, 2010 to 2025). A cluster of metabolic risk factors for CARDIOVASCULAR DISEASES and TYPE 2 DIABETES MELLITUS. "In the CABG group only the presence of dyslipidemia was associated to decreased CD34+/CD144+ counts." (PMID 22214418, 2012). "Previous studies have shown the CD34+ EPCs are best related with cardiovascular risk factors, metabolic syndrome and long-term outcome compared with other subtypes of EPCs." (PMID 23217199, 2012). "We have previously demonstrated an elevation in circulating CD34+ hematopoietic stem/progenitor cells (HSPCs) during development of the metabolic syndrome in otherwise healthy middle-aged individuals." (PMID 36952215, 2023). "Additional dmCpG in regulatory regions of pathobiologically relevant genes included PA-dmCpG within the ACBD5 that is involved in long-chain FA metabolism; CD34, an adipocyte progenitor marker; and CDH18 that hosts variants associated with the metabolic syndrome." (PMID 34025721, 2021). "Moreover, a low CD34+ hematopoetic cell count was associated with CVE and CV death, independently of all potential confounders, in patients with metabolic syndrome." (PMID 20628606, 2010). "Using univariate analysis, reduced circulating EPC level (CD34+KDR+ [cells/105 events]), metabolic syndrome, uric acid, and hsCRP were found to be significant predictors of NAFLD." (PMID 22359630, 2012). "Autologous CD34+ cells hold promise to prevent tissue damage and restore blood flow in diabetic individuals or individuals with metabolic syndrome who may not be ideal candidates for standard revascularization procedures due to a diffuse vascular disease or failed previous revascularization." (PMID 24223881, 2013). "The population of CD34+CD45−CD31− ASCs was significantly more frequent in visceral than subcutaneous adipose depots (10.4 vs 4.1% of the stromal vascular fraction; p < 0.001), but not correlated with BMI or metabolic syndrome traits." (PMID 36952215, 2023).
myxofibrosarcoma (10 papers, 2012 to 2024). A malignant fibroblastic neoplasm arising from the soft tissue. "In examples of cases in which stromal cells are the neoplastic component whose CD34 expression varies, further studies are required for the loss of CD34 expression, degenerative phenomena or both possibilities in the stromal cells of myxofibrosarcoma." (PMID 34298962, 2021). "The histopathological findings of the present case were further consistent with a diagnosis of low-grade myxofibrosarcoma and immunoreactivity to vimentin and CD34, probably reflecting the tumor’s primitive fibroblastic nature." (PMID 23152982, 2012). "Both tumors show an abundant myxoid matrix and there is no helpful immunohistochemical marker to distinguish these tumors - since CD34 might be as well positive in myxofibrosarcomas in particular in superficial locations." (PMID 30111377, 2018). "Pathology revealed a low-grade myxofibrosarcoma with positive vimentin and SMA, partially positive CD-34." (PMID 36091149, 2022).
pulmonary fibrosis (10 papers, 2011 to 2025). Chronic progressive interstitial lung disorder characterized by the replacement of the lung tissue by connective tissue, leading to progressive dyspnea, respiratory failure, or right heart failure. "Subpopulations of lung fibroblasts are known to be CD34+, and previous lineage-tracing experiments in pulmonary fibrosis have shown a hematopoietic contribution to fibroblasts." (PMID 40014797, 2025). "CD34 binds to L-selectin and in L-selectin KO-mice fibrosis induction is hampered in the bleomycin exposure model of lung fibrosis." (PMID 29747640, 2018). "Our data also demonstrate that CD14+ monocytes derived from the circulation of patients with multiple forms of lung fibrosis show robust CD34 expression and display a propensity for collagen production that is reduced when apoptosis is blocked." (PMID 21586112, 2011). "In the recent years obtained results of clinical studies gave us many reasons to believe that there is a relationship between the present of CD34+ fibrocytes and EPCs in PB and degree of severity of pulmonary fibrosis, especially in patients with idiopathic pulmonary fibrosis (IPF)." (PMID 33218322, 2020). "To elucidate the presence of vascular remodelling in the parenchyma of lung during the development of bleomycin-induced pulmonary fibrosis in sheep, we used antibodies against CD34 and collagen type IV on frozen lung sections to identify different structures in blood vessels." (PMID 31882807, 2019). "The mechanistic significance of CD34 on collagen-producing human leukocytes could perhaps best be examined in studies in which these cells are subdivided based on CD34 expression and then adoptively transferred into murine models of experimentally induced lung fibrosis." (PMID 21586112, 2011). "In the lung tissue of mice with pulmonary fibrosis, we found a significant decrease in the number of endothelial progenitor cells (CD45−CD31+CD34+), VEGF2+ cells (CD309+CD45−), and hemangiogenesis precursors (CD45−CD117+CD309+)." (PMID 33171668, 2020).